INS (insulin)
Diseases named in the same sentence as INS in open-access papers (continued):
Sharing a sentence is not in itself a finding about the gene and the disease.
diabetes (continued). "While looking for more suitable sites, the present possibility of providing some diabetes-free years or at least years of reduced insulin needs, still supports the procedure of islet autotransplantation." (PMID 22461976, 2012). "A recent study suggests that defects in hepatic insulin signaling contribute to the development of diabetes in C57BL/KsJ-db/db mice." (PMID 23145054, 2012). "As in human cases, mice deficient in the Wfs1 gene developed glucose intolerance and overt diabetes due to insufficient insulin secretion." (PMID 21915177, 2012). "In order to obtain good glycemic control, self-monitoring of blood glucose (SMBG) is essential in insulin-treated patients with diabetes." (PMID 22397638, 2012). "12,199 persons were identified as diabetes patients treated with anti-diabetic medication or anti-diabetics with insulin throughout the study period." (PMID 22742209, 2012). "In this diabetes type, there is a T cell-mediated destruction of the insulin secreting β-cells of the pancreatic islets." (PMID 22309804, 2012). "Multivariable Cox proportional hazard regression models for all-cause mortality investigated HbA1c in quartiles as well as per 1% increment, diabetes medication in seven categories of insulin and oral hypoglycaemic agents, and disease duration in quartiles." (PMID 22719972, 2012). "Diabetes mellitus signs include hyperglycemia, decreased clearance of glucose, in intravenous tolerance tests, reduced insulin secretion and increased serum lipids." (PMID 22257465, 2012). "The cross-sectional, multinational DAWN (Diabetes Attitudes Wishes and Needs) study examined patients’ and healthcare professionals’ attitudes regarding insulin initiation." (PMID 22999494, 2012). "When the insulin secretory defects are superimposed over an increased need for insulin as in old age, impaired glucose homeostasis, glucose intolerance, and diabetes can result." (PMID 22675349, 2012). "Most patients recalled being referred by their GP to the diabetes centre for education when they were first diagnosed and for stabilisation when first commencing insulin." (PMID 22413897, 2012). "As parameters of metabolic syndrome, we measured the serum levels of insulin, leptin, and adiponectin, because insulin and leptin levels are increased while adiponectin level is decreased in obesity and diabetes." (PMID 22587351, 2012). "Some studies have explored the relationship between insulin and cognitive disease among patients with diabetes." (PMID 22800811, 2012). "Since insulin effectiveness is reduced in diabetes, research into other signalling pathways that support insulin actions or that reduce blood glucose is ongoing." (PMID 22443187, 2012). "Insulin resistance with elevated circulating insulin level is a cardinal feature of type 2 diabetes mellitus at the early stage, which has always been suggested as the etiology of diabetes-related cancer." (PMID 23300866, 2012). "The biggest potential downside to insulin pump therapy is being tethered to a device, and the fact that the presence of this device is a constant reminder that one has diabetes." (PMID 23098076, 2012). "Before the availability of insulin, the life expectancy of children with diabetes mellitus was short and the prognosis for the adult onset diabetes was very poor." (PMID 23882369, 2012). "In diabetic patients, this insulin cream was able to improve wound healing, offering a genuine, cheap and efficient treatment for this devastating complication of diabetes." (PMID 22662132, 2012). "Transplantation of the transfected cells into mice with streptozotocin-induced diabetes results in insulin expression and the reversal of the glucose challenge." (PMID 22761608, 2012). "Younger patients viewed diabetes as an ‘old people’s disease’ and considered insulin as only needed for the elderly." (PMID 22469132, 2012).
diabetes (continued). "Patient barriers included: perceived failure in diabetes management; feelings of social stigma and pain; less lifestyle flexibility; injection fears; and erroneous beliefs that insulin is addictive or toxic." (PMID 22999494, 2012). "Since skeletal muscle is the predominant tissue responsible for insulin-stimulated glucose disposal and a major site of insulin resistance in diabetes, this finding gives us the beneficial potentials of PR." (PMID 22829857, 2012). "Improving insulin production and beta cell function is therefore a universal goal of diabetes therapeutics." (PMID 22253604, 2012). "About 40% expressed frustration with their current diabetes care and were concerned about progression of the disease, especially the need to increase medication or initiate insulin injections." (PMID 23144900, 2012). "Although the prevalence of diabetes is similar among men and women in the United States, differences in fat storage and hormonal profiles related to insulin resistance exist." (PMID 22796563, 2012). "Diabetes mellitus is a group of metabolic disorders characterized by hyperglycemia resulting from impaired insulin secretion or insulin action or a combination of both." (PMID 23151353, 2012). "The efficacy and safety of insulin degludec (degludec), a new-generation ultra-long-acting basal insulin, was compared with insulin glargine (glargine) in people with Type 1 diabetes mellitus in a 16-week, open-label, randomized trial." (PMID 22150786, 2012). "SMBG, hailed as one of the most important developments in diabetes care since the discovery of insulin, costs the UK National Health Service millions of pounds per year and the cost is rising." (PMID 22416896, 2012). "Protein tyrosine phosphatase 1B (PTP1B) plays important roles in down-regulation of insulin and leptin signaling and is an established therapeutic target for diabetes and obesity." (PMID 23133528, 2012). "One critical contributing factor to obesity induced diabetes is the inadequate insulin secretion resulting from β-cell death." (PMID 23028558, 2012). "In 1998 the UK Prospective Diabetes Study group established that intensive treatment with insulin or with oral medications to maintain nearly normal levels of glycemia markedly reduces chronic complications in type 2 diabetes as well." (PMID 24278682, 2012). "In the present study, by using the HCV infection system, we investigate the possible effect of HCV infection on the fate of MIN6 cells, a mouse insulin-producing pancreatic beta cell line which has been widely used for diabetes research." (PMID 22675572, 2012). "It requires health education to emphasise the progressive nature of diabetes and the eventuality of insulin therapy at early stage of the illness." (PMID 22469132, 2012). "The best method to achieve consistent glycemic control in clinically stable patients with diabetes is with scheduled basal/bolus insulin therapy." (PMID 23209941, 2012). "Of the 106 patients with a previous diagnosis of diabetes, 27 were treated with insulin, 47 with oral hypoglycaemic agents and 32 with diet only." (PMID 22848440, 2012). "Current anti-diabetes drugs are mainly aimed to correct hyperglycemia by promoting pancreatic β-cell insulin secretion, increasing insulin sensitivity, or reducing intestinal glucose uptake and hepatic gluconeogenesis." (PMID 22436702, 2012). "It is possible that some patients with diabetes have inactivating mutations in the insulin/IGFI pathway and thus “suffer” from benevolent diabetes." (PMID 22683661, 2012). "Current treatments of Diabetes both Types I and II include diet modifications, exercise, insulin injection, and glucose-lowering drugs." (PMID 23304164, 2012). "Recent advances in diabetes treatment have been successful in postponing the development of microvascular complications through better glycemic control following intensive insulin treatment." (PMID 23185996, 2012).
diabetes (continued). "The selected patients had started insulin treatment for diabetes between the ages of 20 and 45 years and had maternal first- or second-degree relatives with diabetes, hearing loss or epilepsy." (PMID 22780954, 2012). "Findings from this work highlighted the role of several altered pathological pathways involved in the development of diabetes in the B2R−/−D vs. B2R−/−C mice which included: endothelial injury, oxidative stress, and insulin and lipid metabolism." (PMID 23028588, 2012). "Diabetes mellitus is one of the major global health and economic problem, characterized by high levels of blood glucose resulting from defects in insulin production, insulin action, or both." (PMID 22882757, 2012). "The interrelationship between diabetes and Alzheimer's disease seems to be mutual as neurotoxins termed amyloid beta-derived diffusible ligands have been shown to compromise cerebral insulin signaling." (PMID 22369239, 2012). "Superimposed on the “insulin regulation and diabetes” interactome were differentially expressed miRNAs postulated to regulate its biologic function." (PMID 22629440, 2012). "Yet, mTOR can, at times, alter insulin signaling and lead to insulin resistance in the cardiovascular system during diabetes mellitus." (PMID 22545721, 2012). "Many conventional drugs used to treat diabetes act by improving insulin sensitivity, increasing insulin production, and or by decreasing the level of blood glucose." (PMID 22867128, 2012). "One current theory of the progression of skeletal muscle insulin resistance in diabetes is that accumulation of intramuscular lipids will disrupt insulin signaling pathways and decrease glucose uptake." (PMID 23146593, 2012). "HNF1A-MODY subjects with pre-diabetes have defective glucose-induced beta cell insulin secretion indicative of reduced beta cell mass." (PMID 22808921, 2012). "The multidisciplinary team approach to diabetes care, such as insulin initiation, is considered an essential step towards improvement of patient care." (PMID 22545648, 2012). "Such protective mechanisms would likely be the same as those which would become important under conditions in which low O2-induced ATP release from erythrocytes is defective as occurs in humans with pre-diabetes (high insulin levels) or type 2 diabetes." (PMID 22934004, 2012). "Patients with diabetes are unable to produce or efficiently utilize insulin, resulting in hyperglycemia." (PMID 22800811, 2012). "Then, we will focus preferentially on the protective effect of insulin against diabetes and its long-term complications in CNS, aging/longevity, and age-related neurodegenerative disorders (especially Alzheimer's disease (AD))." (PMID 22500228, 2012). "In the context of diabetes, these numbers are related to the blood glucose levels, time intervals and insulin doses of the patient." (PMID 23497693, 2012). "CFRD is a distinct form of diabetes and its pathophysiology involves a gradual deterioration in insulin secretion and diminished insulin sensitivity, which is accompanied by inflammation." (PMID 22606371, 2012). "Obesity was significantly enriched, and obesity-related diseases (cancer), insulin resistance, and diabetes (insulin-dependent and non-insulin-dependent) were also observed." (PMID 23028990, 2012). "IRS1 knockout mice were growth retarded, but an increase in insulin secretion prevented development of diabetes." (PMID 27335671, 2012). "Herewith, we aim to integrate the metabolic, neuromodulatory, and neuroprotective roles of insulin in two age-related pathologies: diabetes and AD, both in terms of intracellular signaling and potential therapeutic approach." (PMID 22500228, 2012). "The adjusted odds ratios for diabetes, insulin use and use of calcium channel blocker was 1.133 (1.074, 1.195), 1.414 (1.228, 1.629) and 1.147 (1.074, 1.225), respectively." (PMID 22571603, 2012).
diabetes (continued). "The model further predicts how insulin, at concentrations found in pre-diabetes, enhances the activity of PDE3 and reduces intracellular cAMP levels leading to decreased low O2-induced ATP release from erythrocytes." (PMID 22934004, 2012). "In brief, workshop participants identified relevant HTS targets for several biological processes related to diabetes and obesity (insulin signaling, islet cell function, adipocyte differentiation, and feeding behavior in Caenorhabditis elegans)." (PMID 22296744, 2012). "In order to investigate variations in insulin concentration between control mothers and mothers with diabetes, total insulin content of each milk sample (fore + hind milk individually) from each mother was measured using the CMIA technique (n = 199)." (PMID 22500167, 2012). "Sixty percent of control NOD mice (only receiving injections of insulin) developed diabetes at 22 weeks of age (P<0.05)." (PMID 22685592, 2012). "Incretins stimulate insulin secretion from pancreatic β-cells and inhibit glucagon secretion from pancreatic α-cells, which is favorable for the treatment of diabetes." (PMID 22870172, 2012). "PCOS is combined with defects in insulin action and insulin resistance (IR) finally leading to diabetes, and it also displays neuroendocrine dysfunction with exaggerated LH pulsatility, and altered production of adrenal androgen." (PMID 22276997, 2012). "The management of persistent insulin allergy in type 1 diabetes mellitus (T1DM) is particularly complicated because ongoing treatment with insulin is essential." (PMID 22937994, 2012). "PDK2 and PDK4 are both increased in conditions in which insulin levels are low (e.g., starvation and diabetes)." (PMID 23730261, 2012). "On average, normal weight patients were diagnosed with diabetes at a younger age, were more likely to use insulin, and less likely to have hypertension or hypercholesterolemia." (PMID 22927948, 2012). "Insulin therapy is used in the management of diabetes mellitus of all types and the need for insulin depends on the balance between insulin secretion and insulin resistance." (PMID 23199230, 2012). "In the KDM group, we evaluated the influence of the treatment with insulin, duration of diabetes, and the presence of macrovascular complications in quality of life." (PMID 22848215, 2012). "In many patients, β-cells fail to secrete sufficient amounts of insulin to compensate for insulin resistance, and they therefore fail to maintain normal glucose levels, marking the onset of diabetes." (PMID 22761194, 2012). "The management of persistent insulin allergy in type 1 diabetes mellitus is particularly complicated because ongoing treatment with insulin is essential." (PMID 22937994, 2012). "Alterations, such as the lessening (or degranulation) of mature insulin granules and expansion of varied organelles, are frequently noticeable in animal models and humans with diabetes induced by various factors." (PMID 22509386, 2012). "SU are drugs of choice to treat type 2 diabetes mellitus, they close KATP channels by an ATP-independent route, thereby causing insulin secretion." (PMID 22672870, 2012). "Hypertension was recognised only in people treated with antihypertensive drugs, diabetes was recognised in people treated with insulin or oral drugs, and dyslipidaemia was recognised in people treated with statins or fibrates." (PMID 23114009, 2012). "Diabetes is characterized by high levels of blood glucose resulting from defects in insulin production, insulin action or both." (PMID 23202918, 2012). "A failure of insulin to increase hepatic glucose utilization and to suppress hepatic endogenous glucose production is a major factor contributing to hyperglycemia in diabetes." (PMID 23145054, 2012). "Clinical studies on diabetes involving insulin and insulin antibody measurements have been hampered for over twenty years due to discordance in results generated by different laboratories." (PMID 23762638, 2012).
diabetes (continued). "Prior to the introduction of insulin, vigorous exercise was frequently prescribed to control blood glucose concentrations in people with diabetes." (PMID 24278702, 2012). "Glibenclamide has been used for many years to treat diabetes, to stimulate insulin secretion from pancreatic beta cells." (PMID 22882757, 2012). "As possible predictors for HRQOL, the following baseline variables were examined: treatment with insulin, glycated hemoglobin (HbA1c), number of diabetes related complications, number of comorbid diseases, Body-Mass-Index (BMI), depression and HRQOL." (PMID 22292092, 2012). "We show that among the five insulin analogues presently used to treat diabetes, only glargine displays a significantly higher potency than insulin in stimulating IRA/IGF1R and IRB/IGF1R." (PMID 22848683, 2012). "As intended, the two groups of patients with diabetes significantly differed with respect to plasma insulin and glucose concentrations." (PMID 23051145, 2012). "Patients with a previous diagnosis of diabetes mellitus requiring insulin therapy or metabolism alteration were excluded from the analysis." (PMID 23031544, 2012). "The role of insulin in the management of diabetes mellitus cannot be overemphasized and people with diabetes use combinations of different types of insulin to better control and manage their condition." (PMID 23199230, 2012). "The signaling molecule resistin (for resistance to insulin) has enhanced circulating levels during obesity and diabetes." (PMID 22545721, 2012). "Diabetes is a devastating disease provoked by the depletion or malfunction of insulin-producing beta-cells in the endocrine pancreas." (PMID 23326678, 2012). "Conventional diabetes therapy using blood glucose-lowering agents such as sulphonylureas, insulin therapy, α-glucosidase inhibitors, peroxisome proliferator gamma (PPAR-γ) agonists and biguanides has limitations." (PMID 23044503, 2012). "The Actos Now for Prevention of Diabetes (ACT NOW) study showed beneficial effects of the insulin-sensitizing agent pioglitazone on carotid intima-media thickness in individuals with impaired glucose tolerance." (PMID 22720085, 2012). "Elevations of insulin concentration have been shown to precede the development of diabetes and multiple metabolic disorders in large prospective studies." (PMID 22518134, 2012). "Diabetes mellitus (DM) is a chronic disease characterized by dysfunction of secretionand usage of insulin, leading to hyperglycemia." (PMID 29213778, 2012). "Experimental diabetes models can be induced by chemicals that selectively destroy the insulin-producing β-cells in the pancreas." (PMID 22645603, 2012). "Mice with partial inactivation of the Ankrd26 gene develop marked hyperphagia, severe obesity and an unusual form of diabetes in which white adipose tissue preserves its sensitivity to insulin." (PMID 22666460, 2012). "Diabetes mellitus is a group of metabolic diseases characterized by high blood sugar (glucose) levels that result from defects in insulin secretion, or action, or both." (PMID 23497445, 2012). "Type 2 diabetes mellitus (T2DM) is a metabolic disease characterized by an elevated blood glucose concentration that results from inadequate insulin action in insulin-sensitive tissues and from abnormal insulin secretion." (PMID 21716678, 2012). "LP-islets that were transplanted into diabetic rats were able to maintain blood insulin levels and to stimulate fat tissue accumulation to partially recover the fat tissue stores, which are depleted when diabetes is established." (PMID 22383969, 2012). "Significant past medical history consisted of insulin-dependant diabetes mellitus treated with Levemir insulin (18 units once daily) and Metformin (850 mg three times daily)." (PMID 22924049, 2012). "To summarize, assessment of insulin sensitivity is highly valuable in glucose homeostasis research, in the development of drugs for diabetes and in clinical diagnostics." (PMID 22952998, 2012).